MMP2 (matrix metallopeptidase 2)
Diseases named in the same sentence as MMP2 in open-access papers (continued):
Sharing a sentence is not in itself a finding about the gene and the disease.
tumor (continued). "We found that overexpression of Drp1 promoted the fission of mitochondria and attenuated the invasion of tumor cells, while inhibition of mitochondrial fission by Midiv-1 enhanced invasive behavior through upregulation of MMP2/9." (PMID 35463323, 2022). "In the HBx‐expressing MHCC97H xenograft tumour tissues, si2R5C treatment decreased the expression of B56γ, upregulated the levels of p‐AKTThr308, p‐AKTSer473, MMP2, and MMP9 in the si2R5C injection group." (PMID 35811356, 2022). "Genipin also increases the tissue inhibitors of matrix metalloproteases (MMP)-2, a kind of tumor promoter in a variety of cancers, as well as induces caspase-dependent apoptosis in in vitro and in vivo models." (PMID 35628447, 2022). "RASIs have also been reported in tumor angiogenesis inhibition and matrix metalloproteinase-2 (MMP2) reduction." (PMID 35847929, 2022). "First, the POLY-PROTAC NPs with MMP-2-liable PEG coronas elongated the blood circulation of the small molecular PROTACs, while the PEG coronas were cleaved via intratumoural MMP-2 to facilitate PROTAC tumour-specific accumulation and retention." (PMID 35882867, 2022). "The migrative cell number decreased in shNK1R-transfected cells, along with the reduced protein level of vimentin, MMP2 and −14, showing the reduced ability of tumor cell metastasis." (PMID 35013118, 2022). "CXCR4 siRNA and CCR7 siRNA attenuated tumor-derived DNA activation of ERK1/2/MMP2/9 signaling pathways in HCC cells." (PMID 35860597, 2022). "During the development of cancer, MMP9 and MMP2 degrade the basement membrane and promote the metastasis of tumor cell to distant tissues and/or organs." (PMID 35959493, 2022). "We also found that anlotinib inhibited the elevated protein expression of RGC32, N-cadherin, and MMP2 in tumor tissue induced by induced by bevacizumab in tumor tissues." (PMID 35664796, 2022). "When correlating MMP-1, MMP-2, MMP-9, TIMP-1, and TIMP-2 expression in tumor tissue in non-invasive and invasive PTC, we report significant positive correlation between TIMP-2 and MMP-2 in the non-invasive tumor group (rho = 0.378, p = 0.039)." (PMID 36551933, 2022). "Matrix metalloproteinase (MMP) is a type of enzyme that promotes tumor cells metastasis, and MMP-2 and MMP-9 are commonly used as tumor metastasis indicators." (PMID 35957875, 2022). "In an animal model of UM, curcumin treatment resulted in lowered expression of MMP-2 and MMP-9 at both the mRNA and protein level in cancer cells, causing a reduction in tumor size." (PMID 35457074, 2022). "When eHsp90α was identified as essential for tumor cell invasiveness, it was also demonstrated that use of cell impermeable geldanamycin beads (GA-beads) decreased MMP2 activity and invasiveness of cancer cells." (PMID 36060252, 2022). "From the results of the tumor-associated genes analysis, the most significant ten tumor- associated genes such as SNAI2, VCAM, MMP2, BRCA1, PARP1 and MECOM were closely associated with UCPs." (PMID 35090503, 2022). "In tumor cells, the synthesis and secretion of MMP-2 and TIMP-2 are in charge of the neighboring stromal fibroblasts." (PMID 36289525, 2022). "There was an upregulation of HGF and MMP-2 in activated fibroblasts and CAFs compared to the control, suggesting their key role in the adhesion of tumor cells." (PMID 35682890, 2022). "P38 has been reported to activate MMP-2/9 and increase invasive capacity in various types of tumor cells." (PMID 35490254, 2022). "In the same tumor samples, we observed an upregulation of caspase-3, Akt, N-cadherin, MMP-2, HSPA1, and p38 MAPK α subunit in grades II, III, and IV compared to normal tissue." (PMID 34964926, 2022). "On the other hand, ERK1/2 signalling has been found to upregulate urokinase and MMP-2 activity and thus stimulates the invasion of VM-forming tumour cells." (PMID 36224457, 2022). "This led to an upsurge in microglial production of IL-6 and subsequently MMP2, which accelerated tumor migration, invasion, and gliomagenesis." (PMID 35419058, 2022).
tumor (continued). "Among MMPs, MMP‐2 and MMP‐9 are mostly associated with ECM degradation and promote tumour cell invasion and metastasis." (PMID 35775112, 2022). "When used in mice with breast cancer, PEG-FA-Lip cleaves PEG chains in response to MMP-2 in the tumor microenvironment, exposing FA to target 4 T1 cells and M2 tumor-associated macrophages (M2-TAM) at the tumor site." (PMID 36452433, 2022). "CA’s mechanism of action involves preventing reactive oxygen species formation, diminishing the angiogenesis of cancer cells, enhancing the tumor cells’ DNA oxidation, and repressing MMP-2 and MMP-9." (PMID 35355732, 2022). "We also demonstrated that the overexpression of Mmp2 in the LG tumors was required for the activation of the innate immune pathway in the fat body, which was distant from the tumor-bearing tissues." (PMID 36226812, 2022). "In this study, PS externalization on the surface of nanoparticles was regulated by MMP-2 secreted by tumor cells, which rendered an “eat me” signal to TAMs for tumor-specific phagocytosis." (PMID 35183252, 2022). "More importantly, PELI1 knockdown inhibited tumor growth in subcutaneous tumor model accompanied with the decreased expression of Ki-67 and cell metastasis marker MMP2." (PMID 34991623, 2022). "Firstly, we confirmed that dsRNAs against Mmp1 and Mmp2 efficiently depleted the relevant mRNAs in the LG tumor cells." (PMID 36226812, 2022). "KLF4 overexpression was verified to result in the inhibition of tumour cell migration and invasion by reducing the levels of metastasis-related MMP2, MMP9, and N-cadherin." (PMID 36518312, 2022). "On the other hand, cabozantinib exerts its effect inhibiting proteins involved in regulation of extracellular matrix (ECM) remodelling and tumour invasiveness and motility (SDF1, MMP2 and HGF) by cancer-associated fibroblasts (CAFs)." (PMID 35106125, 2022). "Nonetheless, the same authors demonstrated that the expression of matrix-metalloproteinase 2 (MMP2) is required for an efficient tumor targeting of CLTX-CART." (PMID 35267432, 2022). "They found that the BLPNs improved the deep tumor penetration and cellular uptake by MMP-2-mediated dePEGylation." (PMID 34987658, 2022). "In fact, it was observed that MMP-2 was actively expressed in only 3.5% of normal pancreas samples when compared to much higher rates in PDAC tumor cells (55.2%) and PDAC stroma (79.3%), with similar ratios were observed for MMP-7 and MMP-9." (PMID 35884592, 2022). "In penile cancer, enforced expression of CXCL13 stimulates tumor metastasis by inducing the expression of metastasis-related MMP2/MMP9 through STAT3 and ERK1/2 signaling pathways." (PMID 36612163, 2022). "In this process, αvβ3-binding of MMP2 facilitates angiogenesis of tumor—invading endothelial cells, therefore promoting tumor growth." (PMID 35631639, 2022). "Results from the previous study indicated that the covalent conjugation of iRGD via MMP2-sensitive bonds enhanced the accumulation and penetration of the conjugate into tumor cell monolayers and spheroids." (PMID 36015351, 2022). "The most important observation in the research is that exosomes derived from drug-treated tumor cells contribute to a smaller increase in the expression of MMP2 and MMP10." (PMID 36012171, 2022). "Knockdown of MMP2 can enhance the proliferation of T cells and the recruitment of NK cells, to inhibit the tumor growth." (PMID 36172139, 2022). "The free MMP2 level in the MKN45–CAF co‐culture group was considerably higher than that in tumor cells or CAFs alone." (PMID 35901491, 2022). "We previously demonstrated that nuclear Pituitary-tumor transforming-gene 1 (PTTG1), overexpressed in several neoplasms, promotes invasiveness through its transcriptional target matrix-metalloproteinase-2 (MMP2)." (PMID 36230799, 2022). "Activated PSCs secrete a dense ECM that modulates tumor stiffness and invasiveness through increased expression of the type IV collagenase matrix metalloproteinase-2 (MMP-2)." (PMID 36077755, 2022).
tumor (continued). "The abnormal accumulation of succinylated FBN1 leads to the upregulation of extracellular factors, such as MMP2, and promotes various responses, such as the intracellular proliferation signals of tumor cells." (PMID 35901491, 2022). "Considering the poor efficacy of cancer angiogenesis monotherapies, we reasoned combining the inhibition of αvβ3 and MMP2 as a multitarget approach to deliver a synergistic blockade of tumor cell migration, invasion and metastasis." (PMID 35209039, 2022). "ICAM-1 expressed on LSECs promotes the secretion of IL-6, prostaglandin E2, VEGF and MMP2 by tumor cells, which in turn induces HSCs to secrete VEGFA and MMP2." (PMID 35965533, 2022). "Abnormal expression of MMP-2 and MMP-9 is associated with multiple stages of tumour growth, vascular invasion, tumour progression, and metastasis." (PMID 35498401, 2022). "Decreased MMP-2 expression resulting from the upregulation of miR-93 was reported, possibly also inhibiting the proliferation and metastasis of tumor cells." (PMID 36180575, 2022). "MMP2/9 is an important regulator of the degradation of the tumour basement membrane and extracellular matrix, thereby promoting cell migration and invasion." (PMID 35840921, 2022). "We showed that the overexpression of Mmp2 in the mxc tumor LG was sufficient to activate the innate immune pathways." (PMID 36226812, 2022). "The digestion of ECM also promotes the secretion of tumor growth factor beta due to MMP-2, which is involved in tumor proliferation and invasion." (PMID 36547091, 2022). "Administration of bevacizumab causes the dose-dependent accumulation of collagen, MMP-2, and MMP-9, which play important roles in the adhesion process of tumor cell invasion and degradation of the cellular matrix." (PMID 35204054, 2022). "RalA is required for Src-induced phospholipase D (PLD) and MMPs (MMP-2 and 9) activations, thereby promoting tumor formation and cell invasion ability." (PMID 36229838, 2022). "Gpr35ΔMΦ tumours contained substantially less MMP2 and MMP9 compared with AOM/DSS-induced tumours from Gpr35fl/fl mice." (PMID 33758004, 2022). "We believe that LSR upregulates MAPK signaling and promotes cell invasion and migration via MT1-MMP and MMP2 in EC cells in this tumor microenvironment." (PMID 35729527, 2022). "In contrast, lycopene also shows significant anti-angiogenic impact via stimulation of immune response and causes a crucial increase in IL-12 and IFN-γ concentrations and decrease in matrix metalloproteinase-2 (MMP-2) action in the tumour microenvironment." (PMID 35276890, 2022). "Upon the intravenous injection of the vesicles into subcutaneous 4T1 tumor-bearing mice, they accumulated within the tumor area through the MMP-2-mediated cleavage of their corona and NLG919 was specifically released here." (PMID 35335881, 2022). "During the malignant transformation from normal pancreas to PDAC, collagen type I induced MMP-2/9 activity and stimulated tumor invasion." (PMID 36167975, 2022). "MMP-2, which correlates with the tumor grade and vascularity in many cancer types, such as human astrocytoma, is shown to be upregulated by HIF-1-dependent pathways in hypoxia." (PMID 36551540, 2022). "Both MMP-2 and MMP-9 have been linked to tumour growth, cell death, inflammation, bone remodelling, and immunity." (PMID 35408590, 2022). "Serum MMP-2 levels showed a significant relationship with the performance status, tumor stage, SUVmax threshold, and the glycolytic activity." (PMID 36013494, 2022). "MMP-2 belongs to the matrix metalloproteinase family of proteins that can hydrolyze the extracellular matrix and promote invasion of tumor cells." (PMID 35392845, 2022).
tumor (continued). "The treatment of RA suppresses the tumor expansion of pancreatic cells and enhances and suppresses the expression of miR-506 and MMP2/16/Ki-67, respectively." (PMID 36247004, 2022). "Meanwhile, matrix metalloproteinase-2 (MMP-2), another downstream oncogene of STAT3, is also overexpressed in AEG patients and significantly associated with tumor differentiation and pT." (PMID 36225196, 2022). "Important gene-products of the NF-κB pathway involved in the regulation of tumor invasion and metastasis are uPA, MMP-2 and MMP-9." (PMID 36015440, 2022). "Conversely, Mmp2 (tumor progression) and Timp3 (inhibitor of metalloproteinases) mRNA expression was significantly repressed after LLC challenge in Igf1rfl/fl mice, while this repression was milder in CreERT2 mice." (PMID 35688943, 2022). "The resulting PP2A activity, which inhibits the PI3K/AKT/NF‐κB pathway, led to the inhibition of tumour invasion and metastasis via decreasing the expression of MMP2, MMP9, and Snail in MDA‐MB‐231 cells." (PMID 35811356, 2022). "Examples of MMPs playing significant roles in both settings—trophoblast and tumor invasion—are MMP-2 and MMP-9, both known to be important facilitators of invasion." (PMID 35625802, 2022). "The MMP-2-sensitive sequence in the dithiocyclopeptide linker was broken down by MMP-2 overexpressed in the tumor microenvironment, leading to a tumor-specific cleavage." (PMID 35918694, 2022). "Down-regulation of the PI3K/AKT/mTOR/MMP-2/9 pathway can inhibit migration and invasion of tumour cells." (PMID 35840921, 2022). "Cluster 2 was similar to cluster 1 in gene expression; however, the high expression of mmp2 and Hif1a indicated that it was tumor neovascularization endothelial cell (tumor neo vEC)." (PMID 36382024, 2022). "Although several studies have demonstrated the ectopic expression of MMPs in epithelial tumors, only a few of them have presented substantial evidence that the disassembly of basement membrane by MMP2 is required for tumor recognition." (PMID 36226812, 2022). "Taken together, it is obvious that VEGF/VEGFR-2 is a central signaling node that significantly contributes to the tumor-promoting effects of MMPs and CAs, especially MMP-2 and CA II." (PMID 35458618, 2022). "PPD-MEND exhibited a long blood circulation property, while once accumulated in tumor tissues, the peptides were cleaved by MMP-2, resulting in the deshielding of PEG which facilitated the internalization of TOs by tumor cells." (PMID 34466734, 2022). "SiRNA-mediated knockdown of PKM2 resulted in an upregulation of tumor suppressors, including Bad, caspase 7, and E-cadherin, whereas oncogenes, such as MMP-2, MMP-9, HIF1α, and VEGF, were downregulated in the SK-OV-3 cells." (PMID 34131394, 2021). "MMP-2 and MMP-9 have also been associated with tumor stage, lymphatic invasion, lymph node metastasis, and recurrence." (PMID 33773545, 2021). "These cells showed increased expression of genes related to tumor growth (Cox2 and Vegfa), metastasis (Cox2, Mmp2, and Mmp9), and immune suppression (Ido2), indicating that TAM generation in vitro had been successful." (PMID 34900687, 2021). "Evaluation of transcript–protein correlations by the tumorsubgroup revealed that ∼25% of the transcript–proteinpairs often displayed radically different correlations dependent onthe ER status (e.g., PARP1) or tumor appearance (e.g., MMP2)." (PMID 33855848, 2021). "A statistically significant decrease in 3 clusters (1, 11, and 12) was apparent when Mmp2-OE tumor infiltrates were compared with WT infiltrates." (PMID 34032639, 2021). "The six genes of the signature belonged to different functional immune-related groups: antigen presentation (HLA-DPA1 and CD1C), innate immune response (TLR7), type II interferon signaling (IFNB1), tumor marker (MMP2), and proliferation marker (MKI67)." (PMID 34209514, 2021). "The content of serum MMP-2, tumor tissue TLR4, MYD88 were also reduced by Andro treatment with statistical implications (p < 0.05)." (PMID 33967748, 2021).
tumor (continued). "Here, we performed a meta-analysis including 41 studies with 6517 BC patients and evaluated the prognostic values of MMP2/9 expression in tumor cells for BC." (PMID 33568081, 2021). "Previous studies have confirmed that matrine, an important component of CKI, can downregulate the abnormal expression of MMP2 and thus inhibit tumor cell invasion and metastasis." (PMID 34646828, 2021). "Meanwhile, the gelatin was degraded by MMP2/9, the gelatinase overexpressed in tumor microenvironment, and the encapsulated NSC and ICG were released in tumor site subsequently." (PMID 34802438, 2021). "Western blot analysis of MMP2 protein expression in tumor lysates shows that MMP2 levels are significantly decreased in shOrai3 Panc1 tumors in comparison to shNT Panc1 tumors." (PMID 34885048, 2021). "Assessment of malignancy after 4T1 cell line exposed with CuO NPs was based on two indices, including MMP-2 as tumor metastatic potential representative and VEGF as angiogenesis representative for migratory tendency." (PMID 33773555, 2021). "In particular, HEKMs can self-assemble into nanorods under normal physiological conditions, and at the same time transform into nanospheres in the microenvironment of tumor cells through a sensitive response to matrix metalloproteinase 2 (MMP-2)." (PMID 34425823, 2021). "In our current study, a SNP in the tumor budding pathway, MMP2 rs243865, was a strong predictor of OS in KRAS mutant patients." (PMID 34108518, 2021). "Analysis of mRNA expression has also shown that social isolation-induced stress in mice with liver metastases caused an increased expression of MMP-2, MMP-9, MTI-MMP, and uPA in the tumor and liver tissue compared to the control mice." (PMID 33810259, 2021). "Given the fact that PPARγ has been reported to act as a tumor suppressor in several cancers and PPARγ silencing increased the expression of C-myc, NF-κB, CyclinD1, cyclin E, MMP2, and MMP9 in BC cells." (PMID 33777130, 2021). "AP-1 is an important transcriptional factor that regulates MMP-2 transcriptional ability and tumor metastasis." (PMID 34445345, 2021). "Further, all non-tumoral adjacent tissues showed very low activity levels of both pro-MMP9 and pro-MMP2, whereas higher activity levels were detected in the paired tumor samples." (PMID 34830271, 2021). "The expression of MMP-2 and MMP-9 in the cancer tissues is enhanced with the increase of tumor pathological stage (MMP-2: F = 3.884, p = 0.029, MMP-9: F = 3.783, p = 0.032)." (PMID 31882379, 2021). "In breast cancer and rectal cancer specimen, MMP-2/-9 activation was observed to be enhanced in the tumor site in comparison to the adjacent healthy tissue, and correlated with dissemination, cancer progression and treatment outcome." (PMID 34055644, 2021). "Then, to identify the role of BMDCs in the invasion of OSCC, we examined the expression of MMP9 and MMP2 in the invasion front line of tumor specimens by performing IHC staining." (PMID 35008304, 2021). "Numerous differences were observed in different tissue regions, and the results showed that MMP2 was highly expressed in tumor margins compared to the central region." (PMID 34976953, 2021). "Tumor invasiveness has been found to be mediated by the increased activation of matrix metalloproteinase-2 and -9 (MMP-2 and MMP-9), mediated by IL-8 levels, indicating that the IL-8 level is associated with metastatic invasiveness and early recurrence." (PMID 33912192, 2021). "Upregulation of MMP2 and MMP9 is highly associated with tumor progression; thus, both of them are regarded as potential targets for cancer therapy." (PMID 33958583, 2021). "MMP2 can degrade most components of the extracellular matrix and basement membrane 26, 27 and plays an important role in regulating tumor invasion and metastasis 28-30." (PMID 34421349, 2021).